KMT2C (lysine methyltransferase 2C)
Diseases named in the same sentence as KMT2C in open-access papers (continued):
Sharing a sentence is not in itself a finding about the gene and the disease.
head and neck squamous cell carcinoma (3 papers, 2019 to 2022). A squamous cell carcinoma that arises from any of the following anatomic sites: lip and oral cavity, nasal cavity, paranasal sinuses, pharynx, larynx, and salivary glands. "Through analyzing a dataset from The Cancer Genome Atlas (TCGA), we found that reduced KMT2C levels were associated with advanced tumor stage, lymph node invasion, and poor cell differentiation in head and neck squamous cell carcinomas." (PMID 35409657, 2022).
hepatocellular carcinoma (3 papers, 2023 to 2025). A malignant tumor that arises from hepatocytes. "Mechanistically, the CDKN2A locus is a genomic and transcriptional target of KMT2C in hepatocellular carcinoma cells, and KMT2C mediates oncogene-induced apoptosis in a CDKN2A-dependent manner." (PMID 39165358, 2024). "Disruption of Kmt2c cooperates with Myc overexpression in the development of murine hepatocellular carcinoma (HCC), in which MLL3 binding to the Cdkn2a locus is blunted, resulting in reduced H3K4 methylation and low expression levels of the locus-encoded tumor suppressors p16/Ink4a and p19/Arf." (PMID 37261974, 2023).
lung adenocarcinoma (3 papers, 2018 to 2021). A carcinoma that arises from the lung and is characterized by the presence of malignant glandular epithelial cells. "Genetic alterations in FRG1 and KMT2C (MLL3) were both significantly associated with a younger age in patients diagnosed with lung adenocarcinoma, especially after correcting for potential predictors, for example, sex and smoking history." (PMID 30821106, 2019).
renal cell carcinoma (3 papers, 2021 to 2025). "Somatic variants in the KMT2C gene are often identified in renal cell cancer; however, none of the families reported with germline alterations in this gene have had renal cancer." (PMID 39095811, 2024).
brain cancer (2 papers, 2020 to 2024). A primary or metastatic malignant neoplasm affecting the brain. "KMT2C has a tumour suppressive role across many cancer types, and mutations or low expression of KMT2C are associated with poor survival in a wide range of lung, breast, gastric, skin and brain cancers." (PMID 33172502, 2020).
carcinoids (2 papers, 2017 to 2024). "Indeed, mutations in genes involved in chromatin remodeling are detected with a high frequency (~40%) in carcinoids, the most frequent being MEN1 (11–22%), genes of the SWI/SNF complex mostly affecting ARID1A (6–7% of cases) and KMT2C/MLL3 (8%)." (PMID 38893145, 2024).
cholangiocarcinoma (2 papers, 2021 to 2023). A carcinoma that arises from the intrahepatic biliary tree (intrahepatic cholangiocarcinoma) or from the junction, or adjacent to the junction, of the right and left hepatic ducts (hilar cholangiocarcinoma). "A recent analysis of patients aged 15 through 45 years with cholangiocarcinoma demonstrated that younger patients were more likely to carry additional sex combos like 1 (ASXL1) and lysine methyltransferase 2c (KMT2C) mutations compared with older patients with cholangiocarcinoma." (PMID 37212509, 2023).
diffuse large B-cell lymphoma (2 papers, 2019 to 2021). "KMT2D and KMT2C (previously known as MLL2 and MLL3, respectively) encode histone H3K4 methyltransferases and are frequently mutated in diffuse large B-cell lymphoma and follicular lymphoma." (PMID 34638403, 2021).
Fanconi Anaemia (2 papers, 2016 to 2022). "These include variants in genes encoding FANCE, a subunit of the Fanconi Anaemia (FA) nuclear complex; NKX2-1, a transcription factor and negative regulator of the NF-κB signalling pathway; and other recognized oncogenes JAK2, PRDM16, BMPR1A and tumor-suppressor genes KMT2C, FAT4, and LRP1B." (PMID 35954343, 2022).
gastric adenocarcinoma (2 papers, 2022 to 2026). "Based on the observation that loss-of-function mutations of KMT2C and KMT2D (KMT2C/D) are enriched and co-occur in gastric adenocarcinoma, we developed genetically engineered mouse model (GEMM) to conditionally knock out Kmt2c and Kmt2d in gastric epithelial cells." (PMID 42118591, 2026).
hypopharyngeal cancer (2 papers, 2022 to 2023). Carcinoma, predominantly squamous cell, arising from the epithelial cells of the hypopharynx. "However, more adequate descriptive and functional studies are required to fully reveal the pathogenic roles of RBM20 and KMT2C in the pathophysiology of hypopharyngeal cancer." (PMID 36596842, 2023). "Since we observed relatively frequent mutations of KTM2C (MLL3) in our dataset, we analyzed their role, in vitro, by generating a KMT2C-mutant hypopharyngeal cancer cell line FaDu with CRISPR-Cas9." (PMID 35664801, 2022). "Importantly, our results suggest a tumor-suppressive role of KMT2C in hypopharyngeal cancer, similarly as in other solid tumors and hematological malignancies." (PMID 35664801, 2022). "In conclusion, we found possible therapeutic targets for hypopharyngeal cancer, especially RBM20 and KMT2C." (PMID 36596842, 2023). "We performed whole-exome sequencing on 10 patients with hypopharyngeal cancer and screened out some genes that may be related to the pathogenesis of hypopharyngeal cancer, including a great number of novel mutations that have not been reported, especially mutations in RBM20 and KMT2C." (PMID 36596842, 2023).
meningioma (2 papers, 2017 to 2026). A generally slow growing tumor attached to the dura mater. "Here, we demonstrate that KMT2C expression is markedly reduced in high-grade meningiomas and that loss of KMT2C promotes proliferation and invasion in NF2-wild-type meningioma cells." (PMID 41642951, 2026).
small cell lung carcinoma (2 papers, 2024). Small cell lung cancer (SCLC) is a highly aggressive malignant neoplasm, accounting for 10-15% of lung cancer cases, characterized byrapid growth, and early metastasis. "Lysine (K)-specific methyltransferase 2C (KMT2C) is mutated in several cancers and is thought to be a tumor suppressor in small cell lung cancer." (PMID 39000069, 2024).
squamous cell carcinoma (2 papers, 2022 to 2024). A carcinoma arising from squamous epithelial cells. "Mutations in the chromatin remodeling genes KMT2C and KMT2D were reported in cervical adeno‐ and squamous cell carcinomas (19% and 15%, respectively), but were absent in previously reported SCLCs and in the UCSCCs analyzed here." (PMID 33830625, 2022).
thyroid cancer (2 papers, 2019 to 2024). "Thyroid cancer has these types of SNV-drivers present in BRAF in 55.8% of cases, the next qualifying genes being TTN, TTN-AS1, NRAS and KMT2C all with a low incidence rate of 1.3%." (PMID 31530827, 2019).
triple-negative breast carcinoma (2 papers, 2020 to 2024). An invasive breast carcinoma which is negative for expression of estrogen receptor (ER), progesterone receptor (PR), and human epidermal growth factor receptor 2 (HER2). "KMT2C and KMT2D, encoding histone H3 lysine 4 methyltransferases, are among the most commonly mutated genes in triple-negative breast cancer (TNBC)." (PMID 38926506, 2024).
urothelial carcinoma (2 papers, 2018 to 2021). A malignant neoplasm derived from the transitional epithelium of the urinary tract (urinary bladder, ureter, urethra, or renal pelvis).
anaplastic thyroid carcinomas (1 paper, 2021). "In fact, histone methyltransferase genes (KMT2A, KMT2C, KMT2D, and SETD2) are increasingly impaired in poorly differentiated and anaplastic thyroid carcinomas." (PMID 33543394, 2021).
attention deficit-hyperactivity disorder (1 paper, 2019). A disorder characterized by a marked pattern of inattention and/or hyperactivity-impulsivity that is inconsistent with developmental level and clearly interferes with functioning in at least two settings (e.g. at home and at school). "Other hub genes (GABBR2, GRM7, MEF2C, SCN2A, KMT2C, and DAGLA) dysfunction have been reported to contribute to ASD and other psychiatric disorders such as Attention-Deficit Hyperactivity Disorder (ADHD), Huntington’s disease, and Rett-syndrome." (PMID 31649562, 2019).
bipolar disorder (1 paper, 2022). A disorder of the brain that causes unusual shifts in mood, energy, activity levels and the ability to carry out day-to-day tasks. "Among the postzygotic de novo mutations in bipolar disorder, deleterious mutations are enriched in the genes known to cause neurodevelopmental disorders (e.g., KMT2C)." (PMID 38911007, 2022).
breast invasive carcinoma (1 paper, 2019). "Interestingly, a positive correlation between ATM, ATR, BRCA1, BRCA2, and KMT2C expression is also derived from TCGA data GBM, LGG, AML, DLBL, SARC, and breast invasive carcinoma (BRIC) RNA‐seq data." (PMID 30665945, 2019).
Chordoid Meningioma (1 paper, 2024). A WHO grade II, usually recurring meningioma characterized by the predominance of tissues that are histologically similar to chordoma. "Another potential argument for a neoplastic origin for MAM may be that one case of the current series harbored a pathogenic variant of the KMT2C gene, which was previously reported in a subset of chordoid meningiomas." (PMID 38565263, 2024).
cognitive deficits (1 paper, 2025). "Reduced H3K4me2 methylation has been causally linked to the emergence of behavioral and cognitive deficits in other preclinical mouse models relevant to psychiatric and neurodevelopmental disorders, including models that are based on genetic deficiency of Shank3, Setd1a, and Kmt2c." (PMID 40102613, 2025).
dilated cardiomyopathy (1 paper, 2023). Cardiomyopathy which is characterized by dilation and contractile dysfunction of the left and right ventricles. "In addition, in patients and a mouse model, increased KMT2C mRNA and protein levels were linked to dilated cardiomyopathy." (PMID 38139143, 2023).
endometrioid endometrial carcinoma (1 paper, 2022).
essential thrombocythemia (1 paper, 2018). A chronic myeloproliferative neoplasm that involves primarily the megakaryocytic lineage. "In addition to the group of CML patients, we also investigated the expression profile of MLL2/KMT2D and MLL3/KMT2C genes in other myeloproliferative diseases including polycythemia vera (N = 25), essential thrombocythemia (N = 35) and primary myelofibrosis (N = 20)." (PMID 29483845, 2018).
female infertility (1 paper, 2024). Diminished or absent ability of a female to achieve conception. "Consistent with expression data from patient samples, our mouse model revealed that deletion of Kmt2d in uterus led to female infertility due to implantation failure, but knockout of Kmt2c did not." (PMID 39117610, 2024).
Immunodeficiency (1 paper, 2022). Failure of the immune system to protect the body adequately from infection, due to the absence or insufficiency of some component process or substance. "Furthermore, the de novo frameshift variant in KMT2C was detected in a patient with combined immunodeficiency and a neurodevelopmental phenotype, displaying partial phenotypic overlap with Kleefstra syndrome type 2 that has already been associated with de novo LoF mutations in KMT2C." (PMID 36250618, 2022).
lung carcinoids (1 paper, 2021). "Recent data have shown that KMT2C is highly mutated on macrodissected lung carcinoids." (PMID 33159839, 2021).
MALT lymphoma (1 paper, 2021). An indolent, extranodal type of non-Hodgkin lymphoma composed of small B-lymphocytes (centrocyte-like cells). "Inactivation of chromatin remodeling genes are frequently observed in MALT lymphomas, with the most common mutated genes being TET2, KMT2D, CREBBP, TBL1X1, KMT2C, MT2C, EP300, among others." (PMID 35008340, 2021).
metastasis (1 paper, 2023). The spread or migration of cancer cells from one part of the body (where they first appeared) to another.
monocytic leukemia (1 paper, 2023). "PTPN11mut was more common in myelomonocytic and monocytic leukemia, and was more likely to co‐mutate with KRAS, KMT2C, NRAS, U2AF1, NOTCH1, IKZF1, and USH2A mutations than PTPN11wt." (PMID 37937729, 2023).
nicotine addiction (1 paper, 2022). "In addition to KMT2C, miR‐3157‐5p, miR‐6808‐5p, and miR‐6874‐3p also target GRIN2B, which belongs to the amphetamine and nicotine addiction pathways." (PMID 35032098, 2022).
oral cancer (1 paper, 2022). "The results provide evidence that the KMT2C gene’s diversity influences the possibility of oral cancer occurrence." (PMID 35409657, 2022). "Our results also revealed an influence of the KMT2C gene on tumor stage, metastasis on the lymph node, and cell differentiation, which indicated the important role of KMT2C in oral cancer." (PMID 35409657, 2022). "Our future study will focus on understanding the relationship between the KMT2C gene and oral precancer, which might demonstrate the role of KMT2C in the prevention of oral cancer." (PMID 35409657, 2022).
ovarian tumor (1 paper, 2020). "Next, the correlation between XIST and KMT2C and cancer stem cell-related genes in human ovarian tumor tissues was analyzed." (PMID 32943985, 2020).
periodontal disease (1 paper, 2025). "TMB analysis revealed that low TMB correlated with tobacco-related SBS4 and SBS5, whereas high TMB was associated with periodontal disease and mutations in KMT2C, MUC16, and CASP8, as well as the ID-19 signature." (PMID 41154345, 2025).
prostate tumours (1 paper, 2022). "Taken together, these data reveal that loss of KMT2C histone methyltransferase activity in Pten-null prostate tumours not only drives proliferation, but also confers invasive properties allowing tumour cells to invade surrounding tissues and spread to distant organs." (PMID 35354467, 2022).
psoriasis (1 paper, 2025). An autoimmune condition characterized by red, well-delineated plaques with silvery scales that are usually on the extensor surfaces and scalp. "However, when a lysine methyltransferase inhibitor (siKmt2c) was applied, the symptoms of inflammation and hyperplasia were alleviated, indicating that the inhibition of KMT2C can disrupt the immune cycle in immune diseases such as psoriasis." (PMID 40723577, 2025).
schwannoma (1 paper, 2020). A benign, usually encapsulated slow growing tumor composed of Schwann cells. "XRCC2 and MLL3/KMT2C were involved in homologous recombination repair and histone modification, suggesting that loss of DNA damage repair and epigenetic alterations might also play key roles in schwannoma." (PMID 33193598, 2020).
sebaceous carcinomas (1 paper, 2021). "A potential epigenetic driver of sebaceous carcinoma was observed in the current study, as 4/12 (25%) of all sebaceous carcinomas harbored mutations in KMT2C, or lysine methyltransferase 2C, with 2/2 OA tumors harboring missense mutations and 2/2 extraocular tumors harboring deletions." (PMID 34445161, 2021).
T-cell neoplasm (1 paper, 2020). "In addition to epigenetic modifiers implicated in all subtypes of T-cell neoplasm (TET2, DNMT3A, KMT2D, KMT2C, SETD2), recurrent mutations of the FAT1 tumor suppressor gene were for the first time recorded in 39% of cases." (PMID 31028364, 2020).
testis cancer (1 paper, 2024). "Almost all of the top-performing genes were that of over-expression, with PMS2 in THYM; CARD11, LASP1, STIL, POLE, KMT2C, and CLIP1 in testis cancer; ERC1, WRN, OLIG2, FANCC, and ACSL6 in ACC; and SOX2 and NDRG1 in ESCA leading in performance with AUCs ranging 0.832-0.911." (PMID 38491101, 2024).
ureteral neoplasms (1 paper, 2021). "KMT2C serves as one of the key regulators of H3K4 methylation, and inactivation results in the development of ureteral neoplasms in mice." (PMID 34445161, 2021).